MUC1 (mucin 1, cell surface associated)
Diseases named in the same sentence as MUC1 in open-access papers (continued):
Sharing a sentence is not in itself a finding about the gene and the disease.
tumor (continued). "A 16 aa MUC1 peptide conjugated to KLH plus DETOX adjuvant administered to 16 patients with metastatic breast cancer induced ab responses in only three patients, and CTL activity against MUC1-expressing tumor cell lines in seven patients." (PMID 24212946, 2011). "We found that the ability of natural antibodies to bind to tumor cells overexpressing MUC1 correlated significantly to their capacity to mediate ADCC of the same tumor cells." (PMID 24212946, 2011). "According to immunohistological studies MUC1 protein expression is particular high in tumours, where it undergoes changes in glycosylation and distribution." (PMID 21314937, 2011). "Tumoral retention of 131I-anti-MUC1 was visualized with gamma camera images 72 hours p.i. in 2 of 5 mice (one mouse died)." (PMID 21603241, 2011). "On the other hand, the internalisation of MUC1 specific antibodies by tumour cells allows other therapeutic approaches including the delivery of toxic compounds into the tumour cells, e.g. antibody drug conjugates or immunotoxins." (PMID 21264246, 2011). "In vivo assays have shown that mice injected with MUC1 downregulated cells develop smaller tumours when compared to mice injected with the control cells." (PMID 22073229, 2011). "A significant correlation was found between the ability to isolate MUC1-specific B cells from tumor-draining lymph nodes and the presence of circulating abs to MUC1." (PMID 24212946, 2011). "In this study, we constructed a MUC1 aptamer-conjugated nanoparticle with S2.2 for delivery of paclitaxel to MUC1-positive tumor cells, combining the advantages of aptamer as targeting agent and the strengths of nanoparticle as drug carrier." (PMID 21912664, 2011). "In carcinomas, cryptic core peptide epitopes on the MUC1 molecule shed into the tumor microenvironment and the circulation induce humoral and cellular immune responses to the mucin." (PMID 24212946, 2011). "These alterations are likely due to MUC1 downregulation, since MUC1 has been shown to directly conduct signals that alter the transcriptional program of tumor cells." (PMID 22073229, 2011). "The positive expression of MUC1 was the highest of the four mucins investigated, and the expressions of MUC1 and MUC5AC were associated with levels of tumor aggressiveness." (PMID 22027009, 2011). "In different tumor models, MUC1 was shown to regulate cell proliferation by interacting with several proteins such as ER-α, β-catenin and EGFR." (PMID 22073229, 2011). "This suggests that TdLN DCs in LLC+Py group mice are competent to cross-prime peripheral tumor specific T cells, eliciting MUC1-specific immune responses with higher potency." (PMID 21931708, 2011). "Most significantly, the O-glycosylation patterns found in the VNTRs are different between tumour MUC1 and MUC1 expressed by normal epithelial cells." (PMID 21264246, 2011). "Other tumor-associated antigens, such as the adhesion molecule EpCAM, the epithelial mucins CA125 and MUC1, and the Folate Receptor as well as molecules expressed by immune cells such as CD3 and CTLA-4 are under evaluation." (PMID 22235224, 2011). "Human MUC1 is highly immunogenic in mice and its epitope is very clear so that it is convenient for us to examine the tumor Ag-specific immune responses." (PMID 21931708, 2011). "It has been reported that the uptake of heavily glycosylated tumor-antigen MUC1 blocks intracellular processing and presentation and thus the induction of CTL responses." (PMID 24212951, 2011). "Using our tumor mouse model with LLC-MUC1 cells, we assessed the tumor-specific (MUC1 versus irrelevant OVA) production of IFN-γ and granzyme B in TdLN cells by enzyme-linked immunospot (ELISPOT) assay." (PMID 21931708, 2011). "A pilot phase III study with stage II early breast cancer patients receiving oxidised mannan-MUC1 resulted in a significant drop in cancer recurrence: 0% of treated patients had tumor recurrences compared to 27% in placebo-receiving patients." (PMID 24212951, 2011).
tumor (continued). "We next examined the systemic anti-tumor immune response and observed that the number of MUC1-specific IFN-γ-producing cells in the spleen was much higher in the LLC+Py mice compared to the LLC mice." (PMID 21931708, 2011). "In this study, we designed a MUC1 aptamer-based targeted drug delivery system to enhance the delivery of paclitaxel to MUC1-overexpressing tumor cells." (PMID 21912664, 2011). "At the end of experiments, the percentage of MUC1 positive staining cells visualized using MAb C595, in tumor xenografts from combination test, combination control, MAb C595 control and vehicle control groups was <5%, 10∼16%, 30–40% and 70∼80%, respectively." (PMID 21931707, 2011). "Initial evaluation of MUC1 peptide/glycopeptide mono and polyvalent vaccines has shown them to be immunogenic and safe; anti-tumor responses are scarce." (PMID 24212946, 2011). "In the present study, we also demonstrated MUC1 expression on OVCAR-3 tumor xenografts using MAb C595 and confirmed the target antigens (MUC1) exist after OVCAR-3 cells seed in peritoneal cavity." (PMID 21931707, 2011). "TACA, which are abundantly expressed on the MUC1 molecule, play an important role in adhesion/anti-adhesion processes that promote tumor progression." (PMID 24212946, 2011). "MAGE-C2/CT-10 should be added to the list of proposed prognostic tumor progression markers, including MUC1, AZGP1, EZH2, E2F3, Ki67, and CD10." (PMID 21754986, 2011). "Soluble MUC1 inhibits adhesion of MUC1-expressing cells to ICAM-1 suggesting an immunosupressive role for the MUC1 shed into the tumor microenvironment and the high levels of circulating mucin often found in advanced stage disease." (PMID 24212946, 2011). "The cellular uptake experiment showed that Apt-NPs increased the uptake of nanoparticles by MUC1-overexpressing tumor cells." (PMID 21912664, 2011). "In tumour cells, the apical expression of MUC1 is lost and the apolar expression leads to MUC1 presentation over the entire cell surface resulting in an accessibility by systematically administered antibodies." (PMID 21264246, 2011). "Mouse models have previously provided evidence of a direct role of MUC1 in tumor progression in other pathological models despite the fact that Muc1 KO mice develop normally, are healthy and fertile." (PMID 24281201, 2010). "In contrast, most C4-HD tumor cells placed on Matrigel form clusters that are much less polarized, with lower levels of integrin α6, MUC-1 and ZO-1 signal, and hollow tissue structures are rarely seen." (PMID 20520761, 2010). "The biological properties of MUC1, its altered expression and post-translational modifications also confer an important role to MUC1 in tumor progression and metastasis." (PMID 24281201, 2010). "Conversely, genes that are widely overexpressed in tumours like Mucin 1 (Muc1), the protease cathepsin B (Ctsb) and integrin, beta 4 (Itgb4) remained upregulated upon treatment with the dual kinase inhibitor." (PMID 21152443, 2010). "The enhanced cancer cell homotypic aggregation by galectin-MUC1 interaction increases the survival of the tumour cells under anchorage-independent conditions by allowing them to avoid initiation of anoikis (suspension-induced apoptosis)." (PMID 20565834, 2010). "In this study, immunization of MUC1.Tg mice with WT-FCs, IKO-FCs, IIKO-FCs, or I/IIKO-FCs provided 100%, 76.6%, 61.5%, and 15.4% protection, respectively, against tumor challenge with MC38/MUC1 tumor cells." (PMID 20182533, 2009). "Many studies have shown that the antibody responses to MUC1 play little role in tumor protection, if any." (PMID 19534821, 2009). "We report here the development of a conditionally replicating adenovirus (CRAd) in which the E1a gene is driven by the tumor-specific promoter MUC-1." (PMID 19635153, 2009). "The MUC1 immunotherapy literatures indicate that cellular immune responses are required for tumor protection." (PMID 19534821, 2009).
tumor (continued). "We used a transcriptional-regulation method placing the E1A gene under control of the tumor-specific promoter MUC-1." (PMID 19635153, 2009). "In this CRAd, the E1a gene is driven by a 0.726-Kb version of the tumor-specific MUC-1 promoter spanning nt2188 to nt2914." (PMID 19635153, 2009). "MUC1 glycopeptides, MUC1 glycoprotein and STn formulations were used as immunogens in an MUC1 transgenic model before challenging with the STn-expressing tumour cells." (PMID 19436292, 2009). "AS1402 is a potent inducer of antibody-dependent cellular cytotoxicity (ADCC), specifically against MUC1-expressing tumor cells." (PMID 19811637, 2009). "We have used a double transgenic mouse model expressing polyomavirus middle T oncogene and human MUC1 as self-antigen to determine the preventive effect of a DCs/tumor fusion cell vaccine." (PMID 20182533, 2009). "Osteopontin was homogenously expressed in the tumour, similar to MUC1 as detected with HMFG2 or 5E5 antibody." (PMID 19436292, 2009). "Here we used different immunogens to target STn in an MUC1 transgenic mouse model of tumour challenge." (PMID 19436292, 2009). "This phenomenon has been extensively studied on MUC1 mucin where the aberrant glycosylation found in tumor cells indicates the appearance of novel glycan epitopes (e.g. STn) as well as the unmasking of peptide sequences (rev." (PMID 19715603, 2009). "The fusion vaccine provided protection against challenge with MUC1-positive tumor cells and mediated regression of established tumors in the mice." (PMID 20182533, 2009). "One week after the last injection, the mice were challenged with RMA tumour cells expressing human MUC1 under a CMV promoter." (PMID 18253127, 2008). "In summary, we have found that the predominant form of the MUC1 protein on the surface of tumor cells and tissues is a low molecular weight species that we call MUC1*." (PMID 18446242, 2008). "Protection from RMA-MUC1 tumour challenge was achieved in C57Bl/6 MUC1 transgenic mice by immunising with syngeneic DCs pulsed with a MUC1 peptide." (PMID 18253127, 2008). "We were also able to demonstrate that NM23, and in particular the mutant that preferentially forms dimers, like the bivalent antibody, stimulated the growth of MUC1-positive tumor cells." (PMID 18833326, 2008). "This study is the first spontaneous cancer model to address the relative importance of the cytoplasmic tail and tandem repeat domains to MUC1-driven mammary oncogenesis, and suggests that both of these domains are essential for tumor formation." (PMID 21655373, 2008). "The stronger expression of N-acetylglucosaminyltransferases and sialyltransferases in the carcinoma tumors potentially augments the anti-adhesive effect of Muc1 and Muc 4, and contributes to tumor progression." (PMID 18811984, 2008). "A biopsy test that quantifies the amount of MUC1* that is accessible to its activating ligands would be a more accurate prognostic indicator than tests that detect portions of MUC1 that are typically shed from the surface of tumor cells." (PMID 18446242, 2008). "Further, the addition of exogenous NM23 to MUC1*-expressing tumor cells stimulated growth, while siRNA suppression of MUC1 in those same cells, suppressed that stimulation." (PMID 18446242, 2008). "There are several reports presenting data from mouse models that suggest that loading DCs with MUC1-based immunogens can result in tumour rejection in MUC1 transgenic (MUC1.Tg) mice." (PMID 18253127, 2008). "One of the well-known tumor antigens is the epithelial cell mucin MUC1, a transmembrane glycoprotein that is differentially expressed on tumor cells compared with normal epithelial cells." (PMID 19014671, 2008). "NM23 has recently been identified as a ligand for MUC1* that stimulates the growth of tumor cells by dimerizing two MUC1* receptors." (PMID 18833326, 2008). "Tumor cells in our case expressed the apomucins MUC1 and MUC2 Several mucin genes designated MUC genes have been identified." (PMID 18768087, 2008).
tumor (continued). "We therefore generated a MUC1* construct, MUC1*1110 (having only forty-five amino acids of the extracellular domain) to mimic the species found on tumor tissue." (PMID 18446242, 2008). "Rather, they express a low molecular weight cleavage product, MUC1*, which we previously demonstrated has growth factor receptor-like activity on tumor cells." (PMID 18833326, 2008). "To investigate the ability of DCs pulsed with MUC1 peptides to protect mice from challenge with MUC1-expressing tumours, we vaccinated C57Bl/6 MUC1.Tg." (PMID 18253127, 2008). "We show that injection of mice with DCs pulsed with a MUC1 tandem repeat peptide (60-mer corresponding to three tandem repeats) can protect wild-type and MUC1.Tg mice from subsequent challenge with a MUC1-expressing tumour." (PMID 18253127, 2008). "We previously reported that, bivalent Anti-MUC1*, stimulated the growth of MUC1-positive tumor cells, whereas the monovalent Fab fragment of that same antibody potently inhibited growth." (PMID 18833326, 2008). "The use of this novel antibody along with another antibody, VU4H5, that recognizes the high molecular weight soluble fragment, revealed that MUC1* is the predominant species on cultured cancer cells and on tumor tissue and is surface-expressed." (PMID 18446242, 2008). "The study reporting an association between glycosylation and angiogenesis but not PSA level or Gleason grade suggests that MUC1 can indirectly (in this case via neovascularization) influence tumor growth." (PMID 19578514, 2008). "ICAM-1 has been shown to initiate malignant invasion in a number of malignancies via its interaction with apical MUC-1 on circulating tumor cells and this interaction can be enhanced by tumor cytokine activities." (PMID 19662219, 2007). "In order to determine the relative influence of MUC1 and other patient and tumour variables known to affect prognosis, a multivariate analysis was performed using the Cox proportional hazards model." (PMID 17349047, 2007). "For the detection of antigen-specific cells we performed ELISpots with whole-tumour antigens (CA 19.9 and MUC-1) which are expressed in tumour cells of >85% of all patients." (PMID 17667928, 2007). "Significant correlations were found in the "mismatch repair proficient group" between MUC1 positivity and tumour stage and grade." (PMID 17349047, 2007). "Several preclinical models have demonstrated that the T cell dependent therapeutic effectiveness of using recombinant poxviruses expressing CEA or MUC-1 in both transplantable and transgenic model tumor systems." (PMID 18039393, 2007). "Cytoplasmic MUC1 was present in 80% of the tumor cells, which made the tumor more consistent with endometrial primary." (PMID 16409624, 2006). "Here, we present data that confirm a high tumor MUC1 expression in HNSCC which correlates positively with circulating MUC1." (PMID 17064405, 2006). "MUC1 is a mucin that has been detected both in the cytoplasm, plasma membrane and nucleus in different tumor localizations." (PMID 17064405, 2006). "Tissue MUC1 expression from 50 HNSCC tumor samples was studied employing two different anti MUC1 antibodies." (PMID 17064405, 2006). "We concluded that cytoplasmic expression of MUC1 in ECA was unlikely affected by hormonal expression in these neoplasms." (PMID 16409624, 2006). "Possibly, tumor cells produce MUC1 mucin which is liberated to the circulation and captured by IgG antibodies forming MUC1-IgG-CIC." (PMID 17064405, 2006). "Tumor derived MUC1 is known to induce cellular and humoral specific immune responses in cancer patients." (PMID 17064405, 2006). "Another interesting conclusion is that poorly differentiated tumors are inversely correlated with tumor and serum MUC1 detection." (PMID 17064405, 2006). "In contrast, MUC1 overexpression in the mammary gland drives tumor formation, indicating that MUC1 is a true oncogene." (PMID 16846534, 2006).
tumor (continued). "The humanised HMFG-1 immunoglobulin has been extensively developed as a clinical immunotherapeutic agent for MUC1 expressing tumours." (PMID 16265351, 2005). "The tumor cells and intraluminal mucin were diffusely expressed MUC1 and MUC5AC and only focally expressed MUC2." (PMID 15907218, 2005). "Iodine-123-labelled HMFG-1 was successfully used to detect MUC1 positive tumours in patients with primary and metastatic lesions of ovarian, breast and gastrointestinal cancer." (PMID 16265351, 2005). "In MUC1, alteration in glycosylation patterns leads to tumor-specific peptide epitopes that are exposed in cancerous cells." (PMID 16188033, 2005). "The tumor cells and intraluminal mucin were diffusely expressed MUC1 and MUC5AC suggesting gastric foveolar phenotype." (PMID 15907218, 2005). "When fusing the scFv to the recombinant ribonuclease rapLRI, only the fusion protein generated with the stable mutant scFv was able to kill MUC1+ tumour cells with an IC50 of 80 nM." (PMID 15150594, 2004). "Although the scFv showed specific binding to MUC1+ tumour cells, its half-life in human serum at 37°C was less than 2 h (data not shown)." (PMID 15150594, 2004). "MUC1 immunoreactivity was observed at the apex of occasional tumour cells delimiting mucosecreting glandular tubes in HID25 and in HID19 tumours." (PMID 14760390, 2004). "MUC1-positive MCF7 tumour cells were incubated with C595scFv-Fc-IL2 fusion protein and IL2, respectively, and cocultured with resting NK cells." (PMID 12966437, 2003). "Taken together, the fusion proteins C595scFv-Fc and C595scFv-Fc-IL2 specifically bind to MUC1-positive tumour cells via the anti-MUC1 scFv domain, the C595scFv-Fc-IL2 protein binds in addition via IL2 to CD25+, activated lymphocytes in vitro." (PMID 12966437, 2003). "The fusion protein, however, provides a specific tool to increase stimulatory signals to both activated T and resting NK cells in the vicinity of MUC1-positive tumour cells in order to improve the antitumour immune response." (PMID 12966437, 2003). "The anti-MUC1 scFv-Fc-IL2 fusion protein harbours the C595 scFv domain for targeting IL2 to MUC1-positive tumours." (PMID 12966437, 2003). "Results presented here suggest the C595scFv-Fc-IL2 fusion protein as suitable immunocytokine for the specific immune modulation in the vicinity of MUC1-positive tumours." (PMID 12966437, 2003). "The purpose of this study was to engineer a novel immunotherapeutic reagent that is directed to MUC1-positive tumour cells and activates effector responses of NK cells." (PMID 12966437, 2003). "Patients with MUC1-positive tumours develop both humoral and cellular immune responses against determinants on the MUC1 antigen from malignant cells as measured by in vitro parameters." (PMID 12966437, 2003). "These properties make the C595scFv-Fc-IL2 fusion protein a suitable candidate for the immunotherapy of MUC1-positive tumours." (PMID 12966437, 2003). "The fusion protein binds to MUC1-derived peptides and to MUC1-positive tumour cells with the same specificity as does the C595 monoclonal antibody." (PMID 12966437, 2003). "As MUC1 is secreted by tumour cells, determination of the levels of MUC1 antigen in the blood has been exploited as a measure of tumour burden and changing levels as a reflection of the response to therapy." (PMID 12966437, 2003). "The fusion proteins were furthermore assayed by flow cytometry for binding to MUC1-expressing tumour cells." (PMID 12966437, 2003). "This set of experiments demonstrates that the C595scFv-Fc-IL2 fusion protein bound to MUC1-positive tumour cells activates resting NK cells to tumour cell lysis." (PMID 12966437, 2003). "Moreover, to better highlight the differences in metabolic pathways, we selected primary tumor samples derived from patients that showed a CR versus PD and stratified the tissues according to MUC1 expression." (PMID 41533164, 2026).